IL10 (interleukin 10)
Diseases named in the same sentence as IL10 in open-access papers (continued):
Sharing a sentence is not in itself a finding about the gene and the disease.
Hypercholesterolemia (14 papers, 2007 to 2026). An increased concentration of cholesterol in the blood. "As observed in the HCD group, hypercholesterolemia causes lung inflammation through elevated IL-1β and IL-6 levels, which are physiologically compensated by increased IL-10 levels." (PMID 37082028, 2022). "In this study, hypercholesterolemia resulted in an increase of IL-1β, and IL-17, with little effect on IL-10." (PMID 35928361, 2022). "In conclusion the present observations demonstrate that hypercholesterolemia leads to activation of an unopposed Th1 immune response in lymph nodes draining atherosclerotic plaques, whereas this response in the spleen is balanced by a concomitant activation of IL-10 expressing Th2 cells." (PMID 21126329, 2010). "To further asses the effect of hypercholesterolemia on the balance between Th1 and Th2 cells we analyzed the release of IFN-γ, IL-4 and IL-10 from cultured splenocytes exposed to ConA." (PMID 21126329, 2010). "It is worth mentioning that the mean IL-10 concentration in this population is above the basal concentration reported in patients with hypercholesterolemia (1.07 ± 0.55 pg/ml), in addition to showing an anti-correlation with LDL levels, highlighting the IL-10 role in an anti-atherogenic process." (PMID 36860987, 2023). "Similarly, some studies evaluating LDL apheresis performed in patients with familial hypercholesterolemia, have shown a decrease in TNF-α and soluble cell adhesion molecules and an increase in IL-10." (PMID 36614906, 2022).
irritable bowel syndrome (14 papers, 2013 to 2025). Irritable bowel syndrome (IBS) is a chronic functional condition of the lower gastrointestinal (GI) tract characterized by abdominal pain or discomfort and disordered bowel habit (diarrhea, constipation, or fluctuation between the two). "G allele Toll-like receptor-2 gene Arg753Gln (rs5743708) and AA genotype interleukin-10 gene-1082A/G (rs1800896) polymorphisms can be the marker of the emergence of adenomatous polyps of the colon concomitant with irritable bowel syndrome." (PMID 37404119, 2023). "Experiments on knockout deficient IL-10 mice spontaneously develop inflammatory syndromes as Irritable bowel syndrome (IBS)." (PMID 33142764, 2020). "AA genotype interleukin-10 gene-1082A/G (rs1800896) polymorphism in the irritable bowel syndrome patient (χ2 = 33.97, 4.0E-8) can be considered as the risk for adenomatous polyps of the colon in irritable bowel syndrome." (PMID 37404119, 2023). "In fact, experiments on IL-10 deficient knockout mice spontaneously develop inflammatory syndromes such as irritable bowel syndrome (IBS)." (PMID 33806624, 2021). "The pro-inflammation property of IL-10 has been reported in conditions such as irritable bowel syndrome, cancer and severe SARS-CoV-2 infection." (PMID 37384753, 2023). "Veillonella levels have been found to be higher in patients with irritable bowel syndrome, and the lipopolysaccharide (LPS) produced by Veillonella could stimulate the release of TNF-α, IL-1, IL-6 and IL-10 within Toll-like receptor (TLR) pathways." (PMID 37208752, 2023). "Patients with irritable bowel syndrome (IBS) who were treated with B. infantis 35624 reported that alleviation of symptoms such as abdominal pain and distention and presented a normalized ratio of the immunomodulatory cytokines IL-10/IL-12." (PMID 28503135, 2017). "Additionally, an earlier study on irritable bowel syndrome (IBS) revealed beneficial systemic and immunomodulatory effects of probiotics, with a notable normalization of the interleukin-10 to interleukin-12 ratio observed exclusively in IBS patients treated with Bifidobacterium infantis 35624." (PMID 40315198, 2025). "Interestingly, only individuals with irritable bowel syndrome who received Bifidobacterium infantis 35,624 exhibited a normalization of the interleukin-10 to interleukin-12 ratio." (PMID 34359543, 2021).
metastatic melanoma (14 papers, 2011 to 2025). A melanoma that has spread from its primary site to another anatomic site. "Research on metastatic melanoma patients undergoing anti-PD-1 therapy identified a higher IFN-γ/IL-10 ratio in responders, suggesting its potential as a predictive tool for therapeutic outcomes." (PMID 40572779, 2025). "We detected upregulated production of TNFα and IL-10 by WM1617 metastatic melanoma cell-line-educated-moDCs." (PMID 36194602, 2022). "We detected significant differences in the IL-10-producing lymphocyte activation capacity between metastatic melanoma cell lines and MDA/HT29 adenocarcinoma cell lines." (PMID 36194602, 2022). "Fourth, in a metastatic melanoma model, we examined the importance of removing the monocytic brake in a prophylactic treatment consisting of anti-IL-10, tumor peptides and Poly I:C." (PMID 34691085, 2021). "IL-10+ B cells were also present in all 23 metastatic melanoma samples (100%)." (PMID 34359321, 2021). "This could lead to immune suppression effect in metastatic melanoma patients with high IL-10 expression in PBMCs by using the PD-1 blockade agents." (PMID 33077770, 2020). "Interestingly, PEA analysis of plasma from metastatic melanoma patients treated with immune checkpoint inhibitors showed association between both VEGF-A and IL-10 and shorter progression free survival." (PMID 31824496, 2019). "IL-10 mRNA and protein have been isolated from a variety of human tumors, including ovarian, breast, renal cell, lung, squamous and basal carcinomas, and metastatic melanoma." (PMID 26217588, 2015). "Since patients with metastatic melanoma display tumor antigen-specific, IL-10-producing T regulatory cells (Tregs), Dr. Palucka queried whether IL-10- producing Tregs could be reprogrammed to become effector cells by DC vaccines." (PMID 21281484, 2011). "Enhanced level of mRNA coding the IL6, IL10, IL12, sICAM-1, sICAM-3, sPECAM-1, and CD40L proteins, whose secretion by the keratinocytes was inhibited by EVs, correlated with the better survival prognosis of the patients with metastatic melanoma." (PMID 35327461, 2022). "In line with this, the bioinformatic analysis of the TCGA database revealed that the high expression of the genes coding IL6, IL10, IL12, ICAM-1, ICAM-3, PECAM-1, and CD40L in tissues of patients with metastatic melanoma correlates with the better survival prognosis." (PMID 35327461, 2022). "Interestingly, in opposed to the WM1617 metastatic melanoma cell line, WM983B-educated moDCs were prone to enhance the IL-10 production of CD4+CD25+ lymphocytes." (PMID 36194602, 2022). "For example, metastatic melanoma and bronchogenic carcinomas produce IL-10 almost exclusively, with little or no secretion by TAMs." (PMID 26217588, 2015).
Multiple Organ Failure (14 papers, 2006 to 2026). A progressive condition usually characterized by combined failure of several organs such as the lungs, liver, kidney, along with some clotting mechanisms, usually postinjury or postoperative. "• Low HLA-DR expression and high IL-6 and IL-10 levels in the first days after surgery were associated with multiple organ failure and death." (PMID 16899122, 2006). "Early high levels of IL-6 and IL-10 and subsequently reduced HLA-DR were all associated with multiple-organ failure and death." (PMID 16899122, 2006). "Hyperthermia (42 °C) was refractory to acetaminophen treatment and deteriorated to multiple organ failure due to hypercytokinemia, with increased serum levels of interleukin-6 (44.6 pg/mL) and interleukin-10 (1010 pg/mL)." (PMID 35219343, 2022). "By trend, patients suffering from multiple organ failure showed higher mRNA levels of IL-8, IL-10, and IL-1ra." (PMID 29445259, 2017). "TNF-alpha, IL-8, IL-10, and IL-1ra mRNA levels were quantified by RT-qPCR and compared to multiple organ failure, 30-day survival, and the induction of therapeutic hypothermia (TH)." (PMID 29445259, 2017). "Studies in mice have revealed that lack of IL-10 leads to multiple organ failure and increases mortality rates." (PMID 40885907, 2025). "IL-8, IL-10, and IL-1ra mRNA levels were higher in patients suffering from multiple organ failure without revealing statistically significant differences." (PMID 29445259, 2017). "Classical inflammatory pathways investigated in the pathogenesis of trauma multiple organ failure such as IL-6, IL-8, and IL-10 were not differentially expressed in patients who would later develop MODS." (PMID 28715416, 2017).
nasopharyngeal carcinoma (14 papers, 2006 to 2025). A carcinoma arising from the nasopharyngeal epithelium. "Nasopharyngeal carcinoma (NPC) is a neoplasm related to inflammation; the expression of cytokines, such as CCL3, CCL4, CCL20, IL-1α, IL-1β, IL-6, IL-8, and IL-10, among others, is presumed to be associated with NPC occurrence and development." (PMID 39483474, 2024). "High IL-10 concentration together with presence of T regulatory cells suppressed T cell responses, thereby promoting nasopharyngeal cancer progression." (PMID 35963999, 2022). "IL-10 expression is highest in nasopharyngeal carcinoma, followed by laryngeal carcinoma." (PMID 38920620, 2024). "In nasopharyngeal carcinoma, EGR3 is activated under hypoxia and contributes to immunosuppression and tumor growth through regulation of IL10 and TGFB1 in regulatory B cells." (PMID 40649712, 2025). "In nasopharyngeal carcinoma (NPC), HLA-G is positively correlated with CD68+ macrophages and IL-10 expression, indicating that HLA-G may regulate immune escape in NPC." (PMID 34868081, 2021). "In nasopharyngeal carcinoma (NPC), cancer cells promote M2 macrophage polarization via the release of TGF-β1 and IL-10, and the tumor-infiltrating M2 macrophages induce the recruitment of Treg cells by chemotaxis, resulting in the induction of the density of Treg cells in TME." (PMID 32408477, 2020). "Expression of IL-8, IL-10 and viral load in nasopharyngeal cancer as a prognostic factor has not been studied in Indonesia." (PMID 25948470, 2015).
neuropathic pain (14 papers, 2014 to 2025). Chronic pain caused by damage to nerve fibers. "In rat models, treatment with Withania somnifera root extract significantly reduced IFN-γ levels while increasing IL-10 expression following SNI-induced neuropathic pain." (PMID 41394145, 2025). "In neuropathic pain models, IL-10 reduces macrophage infiltration and TNF-α levels at nerve injury sites, thereby effectively mitigating pain." (PMID 40165337, 2025). "Taken together, these results strongly indicated that the inhibitory effect of IL-10 activation and cytokine production are responsible for the neuroinflammation induced by chronic morphine injection in neuropathic pain rats." (PMID 24573601, 2014). "In vivo, EGCG can inhibit the expressions of TLR4, NF-κB, HMGB1, TNF-α, and IL-1β, and promote the expression of IL-10 in neuropathic pain rats." (PMID 24692852, 2014). "Proinflammatory cytokines such as tumor necrosis factor-α (TNF-α) can influence long-term behavior in the CCI-induced neuropathic pain model, whereas interleukin-10 (IL-10) as an endogenous anti-inflammatory cytokine can downregulate the nerve's inflammatory reactions to the injury." (PMID 24605047, 2014). "We hypothesised that gabapentin enhanced the morphine anti-nociceptive effect via IL-10 and its downstream HO-1 signal transduction pathway to inhibit pro-inflammatory cytokine expression in neuropathic pain rats." (PMID 24573601, 2014). "In the current study, daily anti-IL-10 and HO-1 antibody injection produced significant pro-inflammatory cytokine expression and attenuated the anti-nociceptive effect of gabapentin in morphine-tolerant neuropathic pain rats." (PMID 24573601, 2014). "Since the activation of the IL-10/β-endorphin pathway can alleviate neuropathic pain, our results suggested that exogenous 4-OI could induce the analgesia by promoting the spinal level of IL-10/β-endorphin in neuropathic pain." (PMID 36311727, 2022). "IL-10 and TGF-β induce therapeutic effects in neuropathic conditions, and their role to the antinociception induced by stem cells in neuropathic pain has been proposed." (PMID 29933760, 2018). "In experimental neuropathic pain models, repeated stimulation has been shown to downregulate pro-inflammatory cytokines (e.g., spinal IL-1β, hippocampal TNF-α), upregulate IL-10, and suppress microglial and astrocytic activation, thereby fostering adaptive plasticity and reducing hypersensitivity." (PMID 41245860, 2025). "EE can relieve neuropathic pain by reducing inflammatory mediators, such as proinflammatory cytokines (IL-1β, TNF-α, IL-6) and chemokines (CCL2, CCL3), among others, increasing anti-inflammatory substances (IL-10, Arg-1, CX3CL1) in the periphery and CNS." (PMID 40190342, 2025). "Microglial MAP kinases can be activated by IL-1β and TNF-α, inducing, via transcription factors such as NFκB, additional production of IL-1β, TNF-α, IL-6, IL-10, TGF-β, PGE2, BDNF, and cathepsin S and promoting the deleterious effects of microglial infiltration and phagocytosis in neuropathic pain." (PMID 24642655, 2014).
oral squamous cell carcinoma (14 papers, 2012 to 2026). "A high proportion of M2 macrophages express TGF-β and IL-10 in oral squamous cell carcinoma which was associated with a reduced patient survival time." (PMID 35784290, 2022). "Dual CD163+CD204+ TAMs possibly play a key role in the invasion and metastasis of oral squamous cell carcinoma (OSCC) by T-cell regulation via IL-10 and PD-L1 production, more valuable than CD163+CD204− TAMs or CD163−CD204+ TAMs." (PMID 33763066, 2021). "Dual CD163+CD204+ TAMs possibly play a vital role in the invasion and metastasis of oral squamous cell carcinoma by T-cell regulation via IL-10 and PD-L1 production, relative to CD163+CD204− TAMs or CD163−CD204+ TAMs." (PMID 33763066, 2021). "On the other hand, these two anti-inflammatory cytokines, IL-10 and IL-13, have been identified as elevated in oral squamous cell carcinoma." (PMID 31973090, 2020). "Increased levels of IL-10 have been observed in patients with solid tumors, including oral squamous cell carcinoma, indicating that this cytokine has a significant role in carcinoma." (PMID 24765208, 2014). "For instance, IL-10 and TGF-β1 derived from CAFs up-regulate the expression of CD163 in monocytes in oral squamous cell carcinoma." (PMID 37254126, 2023). "Secretion of IL-10 and TGF-β was shown to facilitate an immunosuppressive microenvironment by inhibiting T cell proliferation in oral squamous cell carcinoma." (PMID 32986017, 2020). "Interleukin-10 (IL-10) is immunosuppressive in nature preventing the production of TH1 cytokines (such as IL-2, IFN-γ, and TNF-α), increased circulating levels have been found in several types of cancer including oral squamous cell carcinoma and are correlated to a negative prognosis." (PMID 31750257, 2019).
parasite (14 papers, 2015 to 2023). "Low IL-10 expression has been associated with increased fibrogenesis in some parasite infections." (PMID 36534613, 2022). "IL-10 is a well-known anti-inflammatory cytokine, and that during parasite infection, it plays a major role in parasite immunomodulation by suppressing immune responses." (PMID 31681308, 2019). "In our study, mice were sacrificed 8 weeks after infection (61 days post parasite infection), the peak release of Th2-type cytokines such as IL-4 and IL-10, was measured in this work." (PMID 27378927, 2016). "Therefore, a high GM-CSF:IL10 response alongside marked antioxidative enzyme responses were predominant findings in cattle with clinical signs of natural blood parasite infections." (PMID 34438696, 2021). "There is also a need to test whether circulating IL-10 is specific to the parasite infection or could provide a more general indication of intestinal health." (PMID 30463512, 2018). "In contrast, the level of IL-10 cytokines was higher in lethal parasite infection compared to the non-lethal parasite." (PMID 35109868, 2022). "Further, our results showed that IL-10 levels were not significantly altered between LdWT and LdCen−/− infections upon blocking miR-21 indicating that specifically IL-12 regulation through miR-21 occurred in LdWT and LdCen−/− parasite infections." (PMID 31608064, 2019). "Here, we detected high-level IL-10 production in mice after immunization with rEg-TSP1, so we hypothesize that this cytokine might be involved in the regulation of Th2 response and the prevention of a highly polarized Th1 response in which hosts might tolerate the parasite infection." (PMID 26055542, 2015).
abscess (13 papers, 2009 to 2025). An inflammatory process characterized by the accumulation of pus within a newly formed tissue cavity which is the result of a bacterial, fungal, or parasitic infection or the presence of a foreign body. "IL-10 is another cytokine that is implicated in the protection of ZPS-mediated abscess induction." (PMID 21234388, 2010). "In diabetic or immunocompromised hosts, regulatory T cells exacerbate dissemination risks through IL-10-mediated suppression of Th17-dependent neutrophil recruitment, thereby impairing abscess containment." (PMID 41048965, 2025). "Increased expression of anti-inflammatory IL-10 was detected in abscesses of T. medium-challenged mice in comparison to T. phagedenis-inoculated mice (p = 0.02)." (PMID 33007829, 2020). "After an 8-day infection, in consistent with the previous observation, Cj-P1 induced more severe intestinal inflammation in Il10−/− mice compared to Cj-P0, showed as numerous crypt abscesses, extensive immune cell infiltration, and massive goblet depletion." (PMID 33257743, 2020). "ZPS-activated CD4 T cells produce interleukin-10 (IL-10), which is essential to prevent abscess formation and other unchecked inflammatory responses." (PMID 28144234, 2016). "Another study has proven that Bacteroides fragilis-derived polysaccharides (PSAs) may stimulate CD4+ T cells, and these cells can produce IL-10, which may inhibit the occurrence of abscesses and other inflammatory reactions." (PMID 39858150, 2025). "However, the same immunogen, when subcutaneously administered without an adjuvant, induces the activation of immunosuppressive CD4 and CD8 Tregs, both secrete immunosuppressive IL-10 molecules and prevent intra-abdominal abscess formation." (PMID 21234388, 2010). "Also, abscess tissue of infected mice treated with NO-np exhibited reduced levels of IL-4 and IL-10." (PMID 19915659, 2009). "VEOIBD patients with IL10/IL10R signaling pathway deficiency are characterized by early onset refractory diarrhea and severe infectious diseases, oral ulcers, and perianal diseases (abscess, fistula formation, fissure, and skin tags) early in life with severe evolution in some cases." (PMID 33849446, 2021). "Besides having specific effects on the formation of ZPS-induced abscesses, the IL-10-producing CD4 Treg populations seemed to broadly protect the mucosal immune system from diseases mediated by microbial pathogens, such as H. hepaticus-induced experimental colitis." (PMID 21234388, 2010).